INS (insulin)
Diseases named in the same sentence as INS in open-access papers (continued):
Sharing a sentence is not in itself a finding about the gene and the disease.
Glucose intolerance (continued). "Our study had some limitations as it can be assumed that the GDM women already fulfilled the requirement of some degree of glucose intolerance in contrast to most ‘normal’ women, who can adequately respond to the increased demand for insulin during pregnancy." (PMID 34078945, 2021). "The addition of BJ to the hypercaloric diet-fed prediabetic animals promoted a reduction of fed glucose levels, ameliorated glucose intolerance, and enhanced insulin sensitivity." (PMID 34959746, 2021). "At 8 weeks of age (young adult), the nW/sGK males had regained normal body weight, but they still suffered low pancreatic insulin content, low beta cell mass, low glucose-induced insulin secretion and glucose intolerance." (PMID 33525575, 2021). "Nevertheless, maternal DHA supplementation prevented both the glucose intolerance and the rise in serum insulin resulting from consumption of the fc-HFHS diet." (PMID 34578953, 2021). "After 6 weeks of HFD, female mTOR-KOPlacenta displayed glucose intolerance but normal insulin sensitivity at 8 weeks of HFD treatment." (PMID 34032632, 2021). "For example, neural deletion of SIRT1 improves insulin sensitivity and glucose intolerance in mice, while the administration of the pharmacological inhibitor EX-527 improves body weight, food intake, hepatic steatosis and fibrosis in diabetic rats." (PMID 33572672, 2021). "In our study, the male MatOb offspring with a decrease in pancreatic HSG had more apparent glucose intolerance and a significant decrease in islet insulin secretion." (PMID 34108935, 2021). "The authors found that the risk of postpartum conversion rises with advancing degree of glucose intolerance (characterised by decrease of insulin sensitivity and β cell function)." (PMID 34070991, 2021). "For instance, the Fajas group showed glucose intolerance with decreased insulin secretion in addition to other metabolic defects, including hyperlipidemia and enhanced catecholamine secretion." (PMID 34440212, 2021). "Surprisingly, H-Exo treatment led to both SPF and germ-free mice to develop glucose intolerance and reduced their response to insulin." (PMID 33431899, 2021). "Our study suggested that excess NaCl intake accompanied by a HFD attenuated an increase in β-cell mass and resulted in a decrease in insulin secretion and glucose intolerance." (PMID 33730054, 2021). "Accordingly, in this study high fat with or without sugar water supplementation and high starch diets lead to glucose intolerance, and only high starch appears to affect insulin tolerance." (PMID 34444683, 2021). "The development of sex-specific differences in glucose intolerance prompted the detailed evaluation of pancreatic β cell function, which is determined by total β cell mass and insulin secretion." (PMID 34108935, 2021). "The earliest defect in evolution of glucose intolerance is impairment of the first phase insulin response." (PMID 34868882, 2021). "At 5 months, the observed sex-specific deficits persisted, and when challenged with a glucose tolerance test, female Δ9-THC-exposed offspring demonstrated glucose intolerance, despite an augmented insulin response." (PMID 34502436, 2021). "The supplementation with A. muciniphila is sufficient to protect mice against high sucrose‐induced impairment of glucose intolerance by decreasing βCDCA and increasing insulin secretion and FGF15/19." (PMID 34085773, 2021). "The male MatOb offspring developed the highest extent of glucose intolerance and lowest glucose-induced insulin secretion." (PMID 34108935, 2021). "In support of the effects of U. dioica extract on activation of insulin signaling, leaf extract of U. dioica had hypoglycemic effects in normoglycemic rats and attenuated glucose intolerance and improved insulin sensitivity in HFD-fed mice." (PMID 33919569, 2021). "Similar relationships between OC and insulin secretion and glucose intolerance were also demonstrated in human studies." (PMID 33833796, 2021).
Glucose intolerance (continued). "In transgenic mice, insulin in serum was increased at 15 weeks of age and glucose intolerance developed by 25 weeks of age." (PMID 33918805, 2021). "Inhibition of JNK signaling in adipocytes also prevents liver steatosis and thereby promotes insulin clearance and glucose intolerance." (PMID 33917607, 2021). "It is plausible that an excessive intake of NaCl accompanied by a HFD improves insulin sensitivity, while the impairment of insulin secretion results in glucose intolerance." (PMID 33730054, 2021). "The administration of Api markedly improved glucose intolerance and enhanced insulin sensitivity after HFD feeding." (PMID 35046924, 2021). "Insulin concentration, glucose intolerance, HOMA IR, and HOMA beta were also increased significantly withhigher levels of fat and AGEs in all four diets (P<0.05)." (PMID 34155870, 2021). "On the other hand, the adipokine named chemerin, which is secreted and an inactive molecule, is activated by inflammatory and coagulation serine proteases, accentuates glucose intolerance, and makes insulin signaling difficult." (PMID 33807959, 2021). "Glucose intolerance and insulin sensitivity were both reduced in db/db mice treated with macelignan." (PMID 33919569, 2021). "In one of the first longitudinal studies, 32 patients with CF with normal fasting glucose were assessed over 2 years for glucose intolerance and dysfunctional insulin secretion." (PMID 34868882, 2021). "The simultaneous disruption of GHRH and GHR genes resulted in dramatically decreased body weight, higher insulin sensitivity, and glucose intolerance." (PMID 33755309, 2021). "Starting day 3 after the injection, mice that were gavage-given H-Exo for 14 days developed glucose intolerance and had a reduced response to insulin." (PMID 33431899, 2021). "The sex-differences in glucose intolerance and islet insulin secretion persisted in 8-week-old MatOb offspring, suggesting the long-lasting programming effect of maternal obesity." (PMID 34108935, 2021). "In this study, we demonstrated the detrimental effect of maternal SE during pregnancy, which led to smaller body weight, glucose intolerance, and lower plasma insulin level in adult offspring." (PMID 34276421, 2021). "In contrast, circulating insulin levels and glucose intolerance were reduced in obese animals born to DHA-supplemented dams in comparison to the SAL-fcHFHS diet group." (PMID 34578953, 2021). "It is important to point out that other studies report that male offspring display glucose intolerance with impaired insulin secretion." (PMID 35111136, 2021). "Cx36 is expressed in β cells, and Cx36-KO mice develop glucose intolerance via attenuation of glucose-stimulated insulin secretion from the β cells." (PMID 34747371, 2021). "These measures were performed in three-month-old offspring who displayed glucose intolerance and impaired glucose-stimulated insulin secretion." (PMID 34436455, 2021). "Of note, mice deficient for PKD2 enzymatic activity were protected from diet‐induced glucose intolerance and displayed better insulin sensitivity when fed HFD." (PMID 33949105, 2021). "CNIs can induce glucose intolerance by different mechanisms, including a decrease in insulin secretion, an increase in insulin resistance, and toxicity on β-cells." (PMID 33800138, 2021). "It is estimated that when the adaptive expansion of β-cells becomes abnormal, insufficient insulin production results in glucose intolerance." (PMID 33730054, 2021). "The consequent glucose intolerance can further impair insulin sensitivity and promote micro- and macrovascular complications, typical of T2D." (PMID 34943836, 2021). "The F2 progeny of HFD-fed grandparents had lower insulin levels and mild glucose intolerance compared to the F2 from chow-fed grandparents." (PMID 33419045, 2021).
Glucose intolerance (continued). "In the present study, blood glucose analysis revealed marked increase in basal blood glucose level with glucose intolerance, insulin secretion as well as reduced insulin sensitivity, in the HFD fed Juvenile group." (PMID 32595758, 2020). "Rats that were chronically administered RFRP-3 exhibited notable glucose intolerance with simultaneous low insulin sensitivity." (PMID 32328034, 2020). "As such, the loss of muscle mass reduces the quantity of the primary target for insulin, favoring glucose intolerance and gluconeogenesis, which are key to the pathogenesis of NAFLD." (PMID 32351917, 2020). "Experiments on animals have shown that increased concentration of resistin results in reduced insulin response in insulin-sensitive tissues, and leads to glucose intolerance." (PMID 32375231, 2020). "Hyperglycemic and glucose intolerance; reduced islet insulin content and elevated proinsulin levels; increased epididymal fat mass and leptin levels; reduced glucose production, and insulin resistance at later ages, leading to complete onset of diabetes." (PMID 33193056, 2020). "Concurrent with modified glucose metabolism, APPswe/PS1dE9 × db/+ mice led to glucose intolerance, insulin resistance, and altered insulin signaling." (PMID 32503113, 2020). "On the contrary, β-cell-specific Tph1 knockout mice displayed glucose intolerance and impaired insulin secretion with aging." (PMID 32641996, 2020). "Further studies will be needed to determine whether the protection from glucose intolerance that are linked to unabsorbed polymeric PACs from blueberry can be linked to other intestinal targets that are linked to pancreatic beta-cell insulin secretion or hepatic insulin clearance." (PMID 32041991, 2020). "The saturated FA (SFA) including palmitic and stearic acid were found in positive relation with glucose intolerance, impaired insulin sensitivity, impaired insulin secretion and HbA1c." (PMID 32708684, 2020). "Previously we showed that a brief HFHS diet 1 week before and during pregnancy resulted in glucose intolerance, decreased beta cell numbers and serum insulin levels, and increased leptin and triglyceride levels." (PMID 33257770, 2020). "At 0.4 mg/kg, DE-71 produced a less pronounced glucose intolerance and an apparent reduction in insulin and reduced glucagon." (PMID 33093533, 2020). "While HFD increased fasting glucose, and induced glucose intolerance in all animals examined, the defect was most severe in offspring born to hypothyroid mothers, despite similar insulin sensitivity to age-matched controls." (PMID 32472193, 2020). "The current study showed that in spite of being normal weight, increased visceral fat, fasting glucose, insulin secretion and glucose intolerance were observed when rats were fed with HFD starting from 3 weeks old." (PMID 32595758, 2020). "The treatment with FO partially reversed the response to glucose overload (glucose intolerance) triggered by the HF diet while it totally restored the insulin sensitivity." (PMID 32109344, 2020). "High blood glucose levels and glucose intolerance, as a consequence of a defective insulin production/secretion by pancreatic β cells (β-cells) or insulin sensitivity, are the typical clinical features of the disease." (PMID 32265649, 2020). "Aproximately 30% of the sample had values above the recommended values and were being treated for glucose intolerance (20.6% metformin and 7.2% insulin therapy)." (PMID 32028959, 2020). "Here, we show that systemic administration of AAT restores glucose homeostasis in transgenic mice with overexpression of hIAPP in β-cells, which results in glucose intolerance and impaired insulin secretion." (PMID 32229246, 2020). "In a rodent model exposed to HFD, metformin increased serum levels of GDF15 concurrent with reductions in food intake, body mass, fasting insulin and improved glucose intolerance." (PMID 33038072, 2020).
Glucose intolerance (continued). "Ablation of Fxr or Tgr5 results in glucose intolerance and diminished insulin secretion in pregnant mice." (PMID 32661285, 2020). "Mice from the B6 strain show mild glucose intolerance and impaired insulin secretion despite normal insulin sensitivity." (PMID 32673349, 2020). "Together, these findings illustrate that PanIN and PDAC genesis induces selective erosion of islet β-cell mass and attendant remnant islet formation, thereby likely leading to defective insulin secretion and glucose intolerance." (PMID 32371554, 2020). "Our previous studies with global iPLA2β-knockout mice indicated that disturbances in glucose homeostasis, which included glucose intolerance and impaired insulin secretion by pancreatic islet β-cells, occurred as a consequence of iPLA2β gene disruption." (PMID 33080873, 2020). "Metabolic acidosis is also a common complication in patients with end-stage chronic renal failure, which induces insulin insensitivity and glucose intolerance by impairing PI3K activity in the muscle." (PMID 32977552, 2020). "From 12 weeks, WD-fed mice also showed progressively elevated serum AST and ALT, cholesterol, triglyceride and fasting insulin concentrations as well as glucose intolerance." (PMID 32888418, 2020). "Here we demonstrated for the first time that influenza virus infection impairs insulin signaling in liver tissues, which critically regulates glucose metabolism, and induces a tendency toward glucose intolerance." (PMID 32616893, 2020). "Elevation of LPS is associated with low-grade inflammatory pathways, attenuation of insulin signaling, and glucose intolerance." (PMID 32500037, 2020). "β-cell specific constitutively active JNK mice display glucose intolerance, decreased insulin secretion and perturbed insulin signaling within β-cells." (PMID 32183037, 2020). "First insights into the roles of SIDT2 were derived from studies of Sidt2 knockout mice that showed elevated fasting glucose levels, glucose intolerance and decreased serum insulin levels." (PMID 33066450, 2020). "Mice with skeletal muscle-specific BDNF deletion showed significant glucose intolerance and reduced insulin secretion." (PMID 32327658, 2020). "In contrast, aged (10-month-old) L-Mttp−/− mice exhibited glucose intolerance and hepatic insulin resistance along with an increase in hepatic plasma membrane sn-1,2-DAG content and PKCε activation." (PMID 32907986, 2020). "The severe glucose intolerance of the K2-RIP animals is in part a consequence of impairment of insulin release from the pancreatic β-cells." (PMID 31980627, 2020). "In regards to T2D studies, South Asians have been reported to have reduced fat metabolism, muscle fitness, insulin sensitivity, and insulin secretion, all of which support a higher tendency towards glucose intolerance." (PMID 32679915, 2020). "Compared to the CO diet, mice fed with HF diet showed glucose intolerance and a significant increase in the area under the curve by 40% (p < .05), as well as insulin intolerance and a lower glucose disappearance rate by 56% (p < .05)." (PMID 32109344, 2020). "When βTph1KO mice reached 24 weeks, they developed overt glucose intolerance, along with defective insulin secretory response to glucose." (PMID 32641996, 2020). "Deletion of one of the two proteins constituting the MPC (MPC1 and MPC2) results in elevated blood sugar concentrations and glucose intolerance accompanied by impaired glucose-stimulated insulin secretion in both Drosophila and mice." (PMID 33066485, 2020). "The knockout of cTAGE5 in pancreatic β-cells resulted in defective islet structure, reduced insulin secretion, and severe glucose intolerance in mice." (PMID 32101163, 2020). "Endocrinological examination revealed that the glucose intolerance of the affected children is due to reduced levels of secreted insulin." (PMID 32101163, 2020).
Glucose intolerance (continued). "It is well known that the onset of T2D requires biochemical alterations in insulin-sensitive tissues (liver, the skeletal muscle, and the adipose depots), triggering glucose intolerance that finally results in T2D." (PMID 33375647, 2020). "A follow-up study by the same group revealed an excess of catecholamine-induced glucose intolerance through increased insulin resistance with the hyperinsulinemic-euglycemic clamp study in 10 patients with phaeochromocytoma." (PMID 33324347, 2020). "Mac-CM, an inflammatory stimulus, induced glucose intolerance accompanied by impaired insulin sensitivity; genistein reversed these changes by restoring the disturbed IRS1 function, leading to an improvement in GLUT4 translocation." (PMID 33255206, 2020). "An animal study reported that PCSK9-knockout mice exhibited decreased insulin secretion and increased glucose intolerance." (PMID 32708615, 2020). "Glucose intolerance in patients with phaeochromocytoma is often difficult to be well-controlled and insulin therapy is sometimes needed." (PMID 33324347, 2020). "In IR-iNOS−/− mice, we observed significantly higher body weight, BMI, adiposity, blood glucose, HOMA-IR, serum/tissue lipids, glucose intolerance, enhanced gluconeogenesis, and disrupted insulin signaling." (PMID 32806494, 2020). "Age, proportion of women, BMI, waist circumference, and levels of insulin and CPR were positively associated with glucose intolerance." (PMID 31222973, 2020). "R2 mice showed marked glucose intolerance and impaired insulin secretion comparable to C3H-Chr 11NSY mice." (PMID 32703163, 2020). "Patients with Gitelman syndrome have a tendency of glucose intolerance and impaired insulin secretion." (PMID 32758178, 2020). "Glucose intolerance, reduced insulin sensitivity and impaired hypothalamic leptin signaling was identified in male offspring." (PMID 33382823, 2020). "Already at 10 to 11 weeks after castration, the pigs were more insulin resistant, showed higher glucose intolerance and hyperglucagonemia." (PMID 32660013, 2020). "Oxidative stress contributes to the reduction of liver, fat and muscle tissues sensitivity to the insulin action in a mother's body, leading to elevated glucose intolerance." (PMID 33033452, 2020). "Few reports have emerged showing glucose intolerance and elevation in plasma insulin level after HMB administration." (PMID 32098129, 2020). "Obviously, impaired insulin sensitivity and glucose intolerance commenced at the second week of HFD feeding." (PMID 31938068, 2020). "In hepatocytes, 16:1n-7 reduces lipogenesis and improves insulin sensitivity preventing lipid accumulation, while 18:1n-9 promotes lipogenesis and development of steatosis and increases glucose intolerance." (PMID 32284043, 2020). "Administration of NMN, a product of the NAMPT reaction and a key NAD+ intermediate, improved glucose intolerance and hepatic insulin sensitivity in HFD-induced T2DM." (PMID 31208019, 2019). "Prolonged fasting is characterized by low insulin levels, gluconeogenesis, lipolysis, ketogenesis and ketosis (ketone bodies in the blood), glucose intolerance, and hepatic resistance to insulin." (PMID 31406105, 2019). "Pancreatic-specific Bmal1-knockout mice showed glucose intolerance and abnormal glucose-stimulated insulin secretion." (PMID 31851682, 2019). "For example, one study showed that while HFD-induced obese female mice accumulate more subcutaneous and epididymal fat compared with males, they have reduced circulating insulin levels and develop milder glucose intolerance than their male counterparts." (PMID 31315689, 2019). "In this study, 12 weeks of HF feeding was sufficient to induce glucose intolerance and insulin insensitivity." (PMID 31704943, 2019). "In summary, the present study demonstrated that TMSC administration improved HFD-induced glucose intolerance by enhancing insulin secretion." (PMID 31018536, 2019).